DIRC1 (disrupted in renal carcinoma 1)
Gene: Long non-coding RNA gene on chromosome 2 (188,734,155 to 188,790,104, reverse strand). Ensembl gene ENSG00000174325.
Diseases named in the same sentence as DIRC1 in open-access papers:
DIRC1 is named in the same sentence as 3 diseases in open-access papers, as found by Europe PMC text mining. Sharing a sentence is not in itself a finding about the gene and the disease. The quoted sentences say what the papers report.
cancer (1 paper, 2020). A tumor composed of atypical neoplastic, often pleomorphic cells that invade other tissues. "The other two are both associated with cancer: DEC1 and DIRC1." (PMID 32066524, 2020).
tumor (1 paper, 2022). "Disrupted in Renal Cancer 1 (DIRC1) was related to tumor progression and poor prognosis in gastric cancer." (PMID 36456645, 2022).
DIRC1 also shares sentences with these, for which no sentence is quoted: premature ovarian failure (1 paper).